AHR (aryl hydrocarbon receptor)
Diseases named in the same sentence as AHR in open-access papers (continued):
Sharing a sentence is not in itself a finding about the gene and the disease.
Obesity (continued). "The study has shown that clozapine triggered AhR activation, thereby impairing adipogenesis and vasorelaxation in HepG2 cells and adipocytes, which in turn favors the progression of obesity and IR-related metabolic disturbances." (PMID 35454311, 2022). "IFN-γ induces the expression of IDO1, which in turn the metabolites generated as IDO1 dependent manner activate the AHR pathway that contributes to developing obesity." (PMID 35154484, 2022). "Ablation of AhR activity from mature liver and adipose-specific deletion of AhR is helpful in combating obesity." (PMID 35887027, 2022). "The novel AhR antagonist HBU651 exhibited anti-obesity and anti-inflammatory activities in vitro and in vivo." (PMID 36499198, 2022). "It has been shown that AHR plays an important role in HFD induced obesity, fatty liver, glucose intolerance and insulin resistance." (PMID 35154484, 2022). "This dysbiosis can also cause abnormal aryl hydrocarbon receptor (AHR) and GLP-1 resistance and decrease G-protein receptor expression, which result in the development of obesity, insulin resistance, and T2DM (Zhang, 12, 13, 43, 55)." (PMID 36246928, 2022). "In this case, altered IDO1 expression leads to Kyn accumulation, which enhances AhR/STAT3/IL-6 signaling in adipocytes to mediate obesity and insulin resistance." (PMID 35715443, 2022). "With this information, we can identify appropriate tissues for developing and designing drugs to target AhR in combating obesity with minimum side effects." (PMID 35887027, 2022). "AHR plays a crucial role in obesity metabolism by promoting adipogenesis, and it is reported that AHR inhibition leads to reversal of obesity and hepatic steatosis in mice." (PMID 33669862, 2021). "Several reports have highlighted the role of the intestinal AHR, which is mainly expressed in IECs, in diet-induced obesity and metabolic disease." (PMID 35145486, 2021). "Gut microbial tryptophan metabolites have been confirmed as ligands of AHR and influence the progression of obesity, type 2 diabetes (T2D), hypertension, inflammatory bowel disease (IBD), multiple sclerosis (MS), and Huntington's disease (HD)." (PMID 34722615, 2021). "AHR activated by exogenous or endogenous ligands is involved in xenobiotic and immune responses and the pathogenesis of metabolic diseases, such as obesity and cancer (39, –, 41)." (PMID 33622853, 2021). "Metabolic alterations in glucose, fatty acid, and NAD+ metabolism connect AhR signaling and obesity." (PMID 34829665, 2021). "Our work provided clinical data verifying the alternations in AHR expression in PBMCs of both patients with obesity and T2D patients." (PMID 32849564, 2020). "Accumulating evidence reveals that the AHR plays a key role in the crosstalk between obesity and gut microbiota." (PMID 33382356, 2020). "In this study, we made efforts to determine AHR expressions in peripheral blood mononuclear cells (PBMCs) from patients with T2D and metabolically healthy obesity (MHO)." (PMID 32849564, 2020). "AHR continues to be a source of significant interest regarding its role in the development of metabolic syndrome, obesity, steatosis, cardiovascular disease, and diabetes." (PMID 32730300, 2020). "Given that knockout of AHR (whole body or Pdgfrα-Cre mediated) can protect against obesity, it is reasonable to propose that this metabolite is an AHR agonist." (PMID 32730300, 2020). "Up to now, there is a growing body of evidence concerning the role of the AHR signaling in obesity and T2D." (PMID 32849564, 2020). "In line with the theme of this Special Issue on AHR biology, we hope to portray a discrete pathway via which early toxicological studies of TCDD provided the rationale for exploiting the AHR as a therapeutic target in obesity." (PMID 33374508, 2020). "A different story emerges from studies designed to examine the influence of AHR activation in the liver on obesity." (PMID 33382356, 2020).
Obesity (continued). "2, 8-DHQ is a species-specific aryl hydrocarbon receptor agonist and has known benefits in reducing glucose intolerance and fighting obesity." (PMID 33292701, 2020). "AHR signaling, which is required for epidermal γδ T cells to properly develop, becomes reduced during obesity." (PMID 33291435, 2020). "Promoting AhR activity inhibited adipogenesis, obesity, and fatty liver both in male and female mice and protected from the effects of a high-fat diet." (PMID 32067051, 2020). "Our study first identified that AHR transcripts (relative to GAPDH) were notably increased in the PBMCs from both obesity and T2D patients compared with lean healthy subjects with a normal BMI." (PMID 32849564, 2020). "The same phenotype of resistance to diet-induced obesity was described in mice with specific deletion of AhR in pre-adipocytes through the expression of Pdgfrα-Cre." (PMID 33333918, 2020). "Clearly, questions remain as to how AHR mediates effects on obesity and steatosis when mice are on a HFD." (PMID 32730300, 2020). "Another possibility, and one that is favored by our current data, is that an HFD-induced AHR agonist blocks preadipocytes from becoming thermogenically responsive adipocytes, thus decreasing energy expenditure and contributing to obesity." (PMID 32730300, 2020). "The degree of AhR activation raises depend on the severity of obesity due to enhanced inflammatory factors, including TLR2/4- NF-κβ mediated." (PMID 33195370, 2020). "In summary, our studies demonstrate a significant role for AHR in obesity and steatosis in male mice on a high-fat diet." (PMID 32730300, 2020). "Taken together, AHR signaling established a critical role in obesity and glucose intolerance in animal models." (PMID 32849564, 2020). "AHR overactivation directly promotes obesity, hepatic steatosis and insulin resistance under HFD exposure." (PMID 32849564, 2020). "Since AHR is well-established as the major driver of Th22 commitment, our data explained at least partially for the increased Th22 cells in obesity and T2D." (PMID 32849564, 2020). "Up to now, there is a growing body of evidence concerning the role of AHR signaling in obesity and T2D." (PMID 32849564, 2020). "PCB 153, mediated by AhR, can be considered as a ‘secondary strike’ mechanism for obesity/non-alcoholic fatty liver disease in the context of a HFD." (PMID 31638212, 2019). "Accordingly, it has been shown that while AhR transgenic mice were protected from HFD–induced obesity and insulin resistance, they developed severe hepato-steatosis." (PMID 31394746, 2019). "Moreover, AhR-mediated regulation of body weight may result from the combined effects of activation of AhR in various cell types because congenic mice with high AhR signaling activity were more susceptible to diet-induced obesity compared with those with low AhR activity." (PMID 25734695, 2015). "To identify a possible role for the AHR in obesity, we used two mouse models that differ at the Ahr gene." (PMID 22609946, 2012). "The AHR is also activated by dietary components such as fats and fat derivatives, and there is evidence linking the activated AHR to major diseases, including obesity." (PMID 22609946, 2012). "Experimental work in mice has revealed a possible link between AHR signaling and obesity and fat metabolism." (PMID 22609946, 2012). "Notably, in individuals with comorbidities such as obesity and diabetes, AHR overactivity exacerbates insulin resistance, oxidative stress, endothelial dysfunction, and thrombotic risk, contributing to cardiovascular complications." (PMID 40949107, 2025). "Moreover, the activity of the AHR protein has previously been correlated with energy metabolism and the development of metabolic disorders such as obesity and insulin resistance." (PMID 39791758, 2025). "Moreover, a high-fat diet can induce vascular AhR protein expression in mice, and serum AhR levels are higher in individuals with overweight or obesity than in those of normal weight." (PMID 40508196, 2025).
Obesity (continued). "In contrast, knockdown of AhR from adipocytes abolished the effects of Kyn and prevented obesity." (PMID 39944639, 2025). "This suggests that the role of AhR depends on ligands and environment, and that in obesity, pro-inflammatory may be dominant." (PMID 41304481, 2025). "In addition, HBU651, a novel AhR antagonist, ameliorated high-fat diet-induced inflammation and obesity in mice, suggesting the involvement of AhR in the incidence of obesity." (PMID 40943373, 2025). "Experimental studies have revealed that AhR signalling is reduced in obesity." (PMID 39944225, 2025). "Thus, hepatic AhR activation drives mitochondrial dysfunction and obesity, even after a single TCDD exposure." (PMID 40943373, 2025). "In conclusion, quercetin supplementation restores high-fat diet induced gut microbiota dysbiosis, subsequently increasing IPA level to activate the AhR/IL-22 signaling pathway, thereby enhancing intestinal barrier integrity and attenuating chronic inflammation, which collectively ameliorate obesity." (PMID 40308638, 2025). "Moreover, epidemiological studies have revealed that dioxin-mediated activation of AhR is linked to a higher risk of T2DM and obesity." (PMID 40408591, 2025). "However, only tryptamine significantly reduced eWAT weight under HFD feeding conditions, suggesting that its anti-obesity effects are mediated through mechanisms other than AhR signaling." (PMID 39941095, 2025). "Specifically, quercetin ameliorated high-fat diet-induced gut microbiota disruption by reversing the reduction in Lactobacillus abundance and IPA levels, ultimately protecting gut barrier function through activation of the AhR/IL-22 pathway and alleviating chronic inflammation and obesity." (PMID 40308638, 2025). "The alteration of AhR activity promoting the development of obesity could depend on POPs’ mixture composition and individual POP concentrations." (PMID 38255955, 2024). "Remembering that ILC2s regulate adipose function and metabolic homeostasis through the induction of beigeing it is highly likely that AhR depletion in these cells may prevent obesity." (PMID 38931457, 2024). "Therefore, dietary intake of AHR antagonist can prevent fatty liver and obesity in animal models fed with a Western diet." (PMID 39195175, 2024). "Even more interesting, the inhibition of AhR has the potential to reverse obesity." (PMID 38255955, 2024). "Adipose tissue-specific depletion of AhR, protected against diet-induced obesity." (PMID 39301545, 2024). "Our narrative review already exposed the effect of AhR during obesity development." (PMID 38255955, 2024). "Furthermore, it was shown that the inhibition of AHR protects against and cures obesity possibly by lowering the expression of the PPARα-target genes, Cyp1b1, Scd1, and Spp1 in the liver." (PMID 39125436, 2024). "Activating AHR through exposure to environmental chemicals has been documented for its adverse impacts on cardiovascular diseases, hypertension, diabetes, obesity, kidney disease, and non-alcoholic fatty liver disease, as evidenced by both epidemiological and animal studies." (PMID 38731818, 2024). "For example, AhR knockout mice are protected from HFD-induced obesity." (PMID 39301545, 2024). "The activation of the aryl hydrocarbon receptor (AhR), a xenobiotic sensor, by obesogens may contribute to diet-induced obesity through influences on lipid metabolism and insulin resistance acting at various sites, including adipose tissue." (PMID 37443781, 2023). "In line with this hypothesis, AHR is known to mediate metabolism-related syndromes including obesity, insulin resistance, and liver fibrosis, and cardiovascular conditions such as cardiac hypertrophy." (PMID 36029422, 2023). "Since females are prone to obesity etiology and males to diabetes, understanding sex-specific pathophysiological changes may lead to new therapeutic targets, including AhR and its downstream signaling pathways." (PMID 37443781, 2023).
Obesity (continued). "Thus, a better understanding of the contribution of AhR within adipose tissue to systemic metabolism is critical to our understanding of obesity and metabolic illnesses." (PMID 37443781, 2023). "Interestingly, a recent study evaluating the role of AhR specifically in adipocytes showed that adipocyte-specific AhR KO mice are resistant to HFD-induced obesity and partially protected against insulin resistance." (PMID 38136564, 2023). "In experimental animals fed a Western diet, the AHR may disrupt fat metabolism and contribute to obesity." (PMID 36839388, 2023). "The elevated expression of aryl hydrocarbon receptor (AhR) is associated with a variety of different cancers, including MM; however, the role of AhR activity in obesity-associated MM cell growth and survival has not been explored." (PMID 37958428, 2023). "However, there is also evidence about AhR agonists protecting against obesity-related insulin resistance in obese and diabetic animals." (PMID 37239868, 2023). "Thus, there is still a debate concerning the role of tryptophan-derived metabolites and AhR on adipokine modulation in adipose tissue during obesity." (PMID 38136564, 2023). "Both EAT thickness and AhR expression have a close relationship with obesity." (PMID 37749614, 2023). "Further research is required to determine whether C. butyricum C20 and Z1T1 ameliorate obesity by enhancing the crosstalk between the purinergic and AhR signaling pathways." (PMID 37317266, 2023). "Activation of AHR contributes to insulin resistance in HFD induced obesity in mice." (PMID 35154484, 2022). "In this study, AhR transcripts were greatly correlated with insulin resistance and basal β-cell function, indicating a role of AhR-mediated inflammation in the development of obesity and T2DM." (PMID 36418969, 2022). "The next key question is whether Kyn promoting obesity and insulin resistance depends on AhR activation in animals." (PMID 35715443, 2022). "Reduced AhR activity systemically can alleviate obesity, although this may result in many unwanted side effects and thus tissue-specific inhibition is more desirable." (PMID 35887027, 2022). "Furthermore, mice with a low affinity form of AhR (B6.D2) are also protected from diet-induced obesity." (PMID 35887027, 2022). "Moreover, excessive Kyn promotes AhR activity to activate the AhR/Stat3/IL-6 pathway in adipocytes and mediates the development of obesity and insulin resistance." (PMID 35887027, 2022). "AhR activation may also be involved in the occurrence of obesity; however, this mechanism is not fully understood." (PMID 35440600, 2022). "This highlights the complex interaction between AhR and obesity in the pathogenesis of T2DM." (PMID 36418969, 2022). "One study found that blocking AhR reduced obesity in mice on a Western diet." (PMID 35736447, 2022). "Lipids and lipid derivatives, such as oxidized low-density lipoproteins (OxLDL), have been discovered as AhR agonists, which means that the saturated fatty acids found in a typical Western diet activate AhR and contribute to obesity and inflammation in C57B1/6 J mice." (PMID 35268815, 2022). "The authors concluded that AhR activation by KYN may be necessary but insufficient for the development of obesity and that excess caloric consumption is also required for a full manifestation of obesity." (PMID 35440600, 2022). "In addition, other studies demonstrate that inhibition of AHR by the AHR antagonist α-naphthoflavone prevents obesity and fatty liver in male and female mice." (PMID 34418449, 2022). "The inhibition of the AhR prevents Western diet-based obesity." (PMID 35268815, 2022). "AhR is currently being investigated as a potential target for treating obesity." (PMID 35887027, 2022). "Since kynurenine is an AhR-agonist, overstimulation of AhR by higher concentrations of kynurenine might lead to obesity." (PMID 35736447, 2022).
Obesity (continued). "However, metabolic syndromes, such as obesity, diabetes, and high blood pressure of humans and animal models exhibit reduced AHR agonist activity, as shown by lower gut microbiota-derived AHR agonist production, such as of tryptophan metabolites." (PMID 33622853, 2021). "Consistently, AhR−/− mice are protected against diet-induced obesity and glucose intolerance." (PMID 33679800, 2021). "Indeed, dietary exposure to AHR antagonist α-naphthoflavone is capable of inhibiting fatty liver and obesity in mice fed a western diet." (PMID 33382356, 2020). "Increased expressions of the AHR gene may contribute to the overall pro-inflammatory polarization of Th lymphocytes in obesity and T2D patients." (PMID 32849564, 2020). "Inhibiting the expression or action of AhR promoted obesity and fatty liver (reviewed in 97)." (PMID 32067051, 2020). "Moreover, AhR activation is known to decrease serum glucose and triglyceride concentrations, described highly increased in patients suffering from obesity and metabolic syndrome." (PMID 32957545, 2020). "The transcription factor AHR may thus have a plausible role in the interaction between metabolism and pro-inflammatory status of patients in the development of obesity and T2D." (PMID 32849564, 2020). "AhR signaling pathway stimulation also modulates obesity via disrupting fat metabolism." (PMID 33195370, 2020). "Depending on the AHR agonists, different effects on obesity in animals have been observed." (PMID 32730300, 2020). "Furthermore, the AhR agonist indigo has been described to protect against obesity-related insulin resistance through modulation of intestinal and metabolic tissue immunity." (PMID 32957545, 2020). "Studies have shown that the toxicant-activated AHR may disrupt fat metabolism and contribute to obesity." (PMID 32849564, 2020). "Given the high prevalence of obesity and AHR-active air pollution worldwide, and its association with CVD understanding the role of AHR in inflammation-mediated atherogenesis could have a strong impact on the prevention and treatment of atherosclerosis." (PMID 33167400, 2020). "Targeting the AhR may represent an important class of potential therapeutics for obesity-related metabolic complications such as IR." (PMID 30944419, 2019). "Therefore, AhR activation by environmental pollutants has been suggested to promote obesity and related diseases." (PMID 30687113, 2018). "The HFD might increase the availability of endogenous ligands of AhR, such as tryptophan and its derivatives that could contribute to the development of obesity-related NAFLD in mice." (PMID 27713108, 2017). "Elevated KYNA serum concentrations might contribute to development of obesity via KYNA-induced activation of aryl hydrocarbon receptor." (PMID 27738521, 2016). "In conclusion, α-NF increased TG accumulation in mature adipocytes and enhanced mature adipocyte-stimulated tube formation in ECs, suggesting that the AhR may suppress obesity-induced adverse effects, and α-NF abolished the protective effects of the AhR." (PMID 25942489, 2015). "We quantified mRNA abundance of AhR, CYP1A1 (as a marker of AhR activation) and TNF-α (as a marker of inflammation) in adipose tissue of obese mice experiencing weight loss (mice were exposed to PCB-77 during the weight-gain phase of diet-induced obesity)." (PMID 25734695, 2015). "Moreover, results demonstrate a previously unappreciated role for adipocyte AhR to regulate adiposity, adipose inflammation, body weight, and glucose homeostasis in mice with diet-induced obesity." (PMID 25734695, 2015). "Moreover, deficiency of AhR in adipocytes augmented the development of obesity, indicating that endogenous ligand(s) for AhR regulate adipose homeostasis." (PMID 25734695, 2015). "These suggest that the AhR may suppress obesity-induced adverse effects, and its antagonist α-NF abolished the protective effects of the AhR." (PMID 25942489, 2015).